Y_RNA (Y RNA )
Gene: Miscellaneous RNA gene on chromosome 1 (95,125,511 to 95,125,609, reverse strand). Ensembl gene ENSG00000206679.
Homologues: Orthologues: chimpanzee Y_RNA (98% identical). Paralogues in human: Y_RNA (83% identical), Y_RNA (81% identical), Y_RNA (80% identical), Y_RNA (79% identical), Y_RNA (78% identical), Y_RNA (77% identical), Y_RNA (76% identical), RNY1 (75% identical), RNY1P5 (75% identical), Y_RNA (75% identical), RNY1P14 (74% identical), Y_RNA (74% identical), and 91 more.